NF2 (NF2, moesin-ezrin-radixin like (MERLIN) tumor suppressor)
Diseases named in the same sentence as NF2 in open-access papers (continued):
Sharing a sentence is not in itself a finding about the gene and the disease.
osteosarcoma (17 papers, 2011 to 2025). A usually aggressive malignant bone-forming mesenchymal neoplasm, predominantly affecting adolescents and young adults. "NF2 mutations were identified in single human patients; however, comprehensive studies providing frequencies of NF2 gene mutations in human osteosarcoma patients are missing." (PMID 35955749, 2022). "Here, we investigated the role of CD44 in the regulation of drug chemoresistance, using osteosarcoma cells isolated from mice carrying a mutation of the tumor suppressor neurofibromatosis type 2 (Nf2) gene." (PMID 35955749, 2022). "Deletion of the Nf2 gene, encoding Merlin, leads to the generation of highly metastatic osteosarcoma tumors in mice." (PMID 35955749, 2022). "In order to study the relevance of CD44 in mediating chemoresistance, we previously isolated osteosarcoma cells from mice that developed endogenous osteosarcoma, due to a mutation of the tumor suppressor gene Nf2." (PMID 35955749, 2022). "In the current study, we applied osteosarcoma tissues and cells isolated from mice with a mutation of the Nf2 gene, to evaluate the function of CD44 in the resistance to chemotherapy." (PMID 35955749, 2022). "Nevertheless the Nf2-deficient osteosarcomas express additional CD44 splice variants." (PMID 35955749, 2022). "Nevertheless, a broad meta-analysis study demonstrated that NF2 expression is downregulated in a large panel of human osteosarcomas, which is compatible with its function as a tumor suppressor in this tumor type." (PMID 35955749, 2022). "One of the first gene-targeted mouse models noted to develop frequent osteosarcomas is the merlin or Nf2 knockout." (PMID 21403899, 2011). "The role of NF2 in the pathogenesis of human osteosarcoma is less well described." (PMID 35955749, 2022). "Finally, alterations to neurofibromatosis-2 (NF2) have been correlated with increased incidence of several highly metastatic tumors, including osteosarcoma." (PMID 33809018, 2021). "The NF2 mutation was not reported in 14 osteosarcomas analyzed (COSMIC, Aug 2014)." (PMID 26510912, 2015). "This SOX2-Hippo axis has been shown to directly inhibit NF2 and activate YAP, driving cell plasticity in both osteosarcoma and GBM cell lines." (PMID 35119068, 2022). "Due to this inhibitory effect on WWC1 and NF2 transcription, enhanced YAP activity induces the expression of target genes that are important to maintain the cancer stem cell characteristics and differentiation in osteosarcoma." (PMID 33467643, 2021). "In osteosarcoma, the transcription factor SRY-Box Transcription Factor 2 (Sox2) was shown to counteract the Hippo pathway and to restrain its two activating components, WWC1 and neurofibromin 2 (NF2, merlin in Drosophila)." (PMID 33467643, 2021). "However, point mutations or deletions of several tumor suppressor genes, likely to be drivers of osteosarcomagenesis, were observed in a recent report of human osteosarcoma including NF1, NF2 and PTEN, all of which were also recovered in a transposon-based screen for osteosarcoma in mice." (PMID 29056713, 2016).
pleural mesothelioma (17 papers, 2016 to 2026). A neoplasm that arises from the mesothelial cells of the pleura. "As previously reported, NF2-inactivating mutations are among the most common inactivating mutations arising in pleural mesothelioma." (PMID 38136262, 2023). "A total of 30% to 40% of pleural mesotheliomas have somatic NF2 mutations." (PMID 40227645, 2025). "Another study similarly found intra-tumor heterogeneity of NF2 mutation in pleural mesothelioma, suggesting that NF2 mutation is a late event that could lead to more aggressive phenotypes." (PMID 40227645, 2025). "Intra-tumor heterogeneity of NF2 mutation in pleural mesothelioma has also been observed in another study, indicating that NF2 mutation is a late event that may result in more aggressive phenotypes." (PMID 37180489, 2023). "Somatic mutation of NF2 is harbored in 30%–40% of pleural mesotheliomas." (PMID 37180489, 2023). "Copy number loss of BAP1, CDKN2A/B, LAST1/2, and NF2 is frequently found in pleural mesothelioma." (PMID 32545767, 2020). "In our study, NF2 was altered in 32.8% of pleural mesothelioma and 26.5% of peritoneal mesothelioma cases." (PMID 36138075, 2022). "A recent report was published with preclinical evidence supporting the use of quinacrine in pleural mesothelioma, but without any focus on NF2 mutations." (PMID 34621176, 2021). "The five most frequently altered genes in pleural mesothelioma were CDKN2A (48.2%), BAP1 (45.0%), CDKN2B (42.2%), NF2 (32.8%) and MTAP (32.3%), in peritoneal mesothelioma BAP1 (47.9%), NF2 (26.5%), CDKN2A (25.9%), CDKN2B (19.5%), PBRM1 (15.8%)." (PMID 36138075, 2022). "The inactivation of NF2 in malignant Pleural Mesothelioma with mTOR activity aberrantly upregulated, fails to inhibit cell proliferation, leading to a poor prognosis." (PMID 32723974, 2020).
brain tumors (14 papers, 2007 to 2025). "It has been thought for some time that the protein encoded by the neurofibromin 2 (NF2) gene is a key to understand these brain tumors." (PMID 31652973, 2019). "In patients with NF2, the VSs arise bilaterally and coincide with other brain tumors." (PMID 32244314, 2020). "A total of 29 relevant brain tumor genes are indicated on the graph and notably PTEN and MGMT are located on chromosome 10 whereas SMARCB1 and NF2 are located on chromosome 22." (PMID 40136376, 2025).
glioblastoma (14 papers, 2013 to 2025). The most malignant astrocytic tumor (WHO grade IV). "Rather, NF2 mutations may help contribute to poorer phenotypes of glioblastomas, characterized by key mutations in other driver mutations." (PMID 39796693, 2024). "Cancers associated with NF2 mutations include glioblastoma, prostate cancer, and thyroid cancer." (PMID 39796693, 2024). "With glioblastoma tissue that has an overexpression of both NF2 and Ezrin, Ezrin can inhibit Rac1 inhibition, leading to proliferation." (PMID 39796693, 2024). "Another study of glioblastomas found that NF2 was lost in nearly a third of all glioblastoma cell lines and tumors." (PMID 39796693, 2024). "NF2-mutant glioblastomas have several theorized pathways, excluding Hippo signaling, while studies on NF2-mutant prostate cancer simply detail other tumor suppressors that are commonly associated with NF2 in those tumors." (PMID 39796693, 2024). "EZR has been shown to promote tumour progression by modulating the nuclear translocation of YAP in pancreatic cancer and by overexpression in glioblastoma by inactivating the NF2 tumour suppressor, which leads to tumour growth." (PMID 35075167, 2022). "In glioblastoma, Ezrin interacts with and delocalizes the cytoskeletal-related protein neurofibromatosis type 2 (NF2), which carries out opposite activities in tumor growth." (PMID 33240887, 2020). "Here, we report that NF2 suppresses T-antigen protein expression in U-87 MG human glioblastoma cells, which subsequently reduces T-antigen-mediated regulation of the JCV promoter." (PMID 23308224, 2013). "NF2 is a putative tumor suppressor for glioblastoma growth, in that it is lost in many patient samples and cell lines." (PMID 23308224, 2013). "Here, we provide evidence for a novel role of NF2 as an inhibitor of oncogenic JCV T-antigen expression in glioblastoma cells." (PMID 23308224, 2013). "Prostate cancer and glioblastoma alike have studies in human cancer cell lines revealing NF2-mutations, but those studies do not describe any Hippo signaling pathway involvement." (PMID 39796693, 2024). "Here, we show that NF2, specifically its FERM domain, negatively regulates JCV T-antigen protein levels via a proteasome-mediated pathway in U-87 MG human glioblastoma cells." (PMID 23308224, 2013). "Although commonly mutated and involved in several pathways that promote tumor development, NF2 does not seem to play an essential role in the tumorigenesis of glioblastomas." (PMID 39796693, 2024). "Notability, Ezrin, in a complex with NF2, enhances glioblastoma growth independent of its molecular conformation or subcellular localization." (PMID 33240887, 2020). "In glioblastoma, the expression of NF2 was absent in one-third of the cells with concomitant increase in Ezrin expression, which disables Nf2." (PMID 33171868, 2020). "Expression of NF2 has been shown to be absent in certain human glioblastomas and reintroduction can greatly suppress their growth." (PMID 23308224, 2013).
intracranial meningioma (14 papers, 2019 to 2025). A meningioma that arises within the cranial cavity. "Early age at diagnosis, truncating NF2 PVs and the presence of intracranial meningiomas were associated with increased mortality in NF2-related SWN." (PMID 40794298, 2025). "A total of 105 patients (32 males and 73 females) with intracranial meningiomas were recruited in the training and testing cohorts, including 60 patients with NF2 mutation/loss and 45 wild type patients." (PMID 36267986, 2022). "This study aimed to investigate the feasibility of predicting NF2 mutation status based on the MR radiomic analysis in patients with intracranial meningioma." (PMID 36267986, 2022). "Incidentally, there are reports in the literature of mutations at the 5-prime end of the NF2 gene that are associated with increased intracranial meningiomas." (PMID 33445724, 2021). "The results confirm the effectiveness of early implementation and regular monitoring of ONSD measurements via MRI or ultrasound in patients with NF2, particularly those with intracranial meningiomas that affect adjacent venous sinuses." (PMID 40820211, 2025). "Five patients had multiple NF2-related intracranial meningiomas and underwent SRS for IVMs." (PMID 36769714, 2023). "We present a rare case of multiple intracranial meningiomas in the absence of NF2, which we treated at Tata Main Hospital, Jamshedpur." (PMID 35308751, 2022).
tumor predisposition syndrome (14 papers, 2009 to 2026). "Neurofibromatosis type 2-related schwannomatosis is a rare tumour predisposition syndrome caused by loss-of-function pathogenic variants within the NF2 gene, which encodes the tumour suppressor protein merlin." (PMID 42272870, 2026). "Neurofibromin 2 (NF2)-related schwannomatosis (NF2-SWN) is an autosomal-dominant tumor predisposition syndrome." (PMID 40746735, 2025). "Although mosaicism has been documented in several tumour predisposition syndromes, NF2 appears to have the highest recorded number of de novo mosaicism cases." (PMID 37904024, 2023). "In this sense, NF2 continues to demonstrate how systematic molecular and clinicopathologic study of tumor predisposition syndromes may yield substantial biological insights in addition to improvement in clinical care." (PMID 31161239, 2020).
acoustic neuroma (13 papers, 2007 to 2025). A type of benign brain tumor that begins in the Schwann cells, which produce the myelin that protects the acoustic nerve - the nerve of hearing. "In conclusion, bilateral acoustic neuromas associated with NF2 remain one of the most challenging forms of acoustic neuromas." (PMID 36285234, 2021). "Preoperative MRI showed a large right acoustic neuroma, significant regrowth of the left tumor, and several other small enhancing tumors compatible with the NF2." (PMID 36285234, 2021). "Acoustic schwannomas in patients with NF2, radiation-induced meningiomas, dysembryoplastic neuroepithelial tumors (DNETs), and low-grade gliomas (LGGs)/incidentalomas are other entities that can be diagnosed based on typical radiological criteria." (PMID 33821340, 2021). "Moreover, due to the Swedish ICD-coding system, we could only distinguish NF1 from NF2 based on the absence of benign meningioma or acoustic neuroma diagnoses." (PMID 37490289, 2023).
renal cell carcinoma (12 papers, 2016 to 2026). "Renal cell carcinoma studies in humans and mouse models alike have provided evidence for Hippo signaling pathway involvement in the carcinogenesis of these NF2-mutated tumors." (PMID 39796693, 2024). "In both of these cases, renal cell carcinoma, a cancer with a relatively high frequency of NF2 mutation, was high-ranked on the list of considered diagnoses based on standard pathologic assessment." (PMID 27245685, 2016). "Furthermore, genetic alterations in NF2 (the gene encoding merlin) have been implicated in a subtype of renal cell carcinoma known as collecting duct carcinoma." (PMID 39157066, 2024). "Many studies have reported that NF2 enhances the Hippo signaling pathway through phosphorylation, isolation, degradation, and inhibition of YAP/TAZ nuclear translocation, and abnormal Hippo signaling pathway and YAP activation occurs in NF2-deficient unclassified renal cell carcinoma (uRCC) cases." (PMID 36483738, 2022). "In one of these three possible renal cell carcinomas (case P0039), copy loss of TSC1 and a likely loss-of-function deletion in NF2 were detected, strongly suggesting AKT/mTOR pathway was activated." (PMID 27245685, 2016).
nerve sheath tumors (11 papers, 2012 to 2025). "Is a benign, typically encapsulated nerve sheath tumor composed entirely of well-differentiated Schwannn cells, with loss of merlin (the NF2 gene product) expression in conventional forms." (PMID 32244473, 2020).
tuberous sclerosis (11 papers, 2018 to 2025). Hereditary disease characterized by seizures, intellectual disability, developmental delay, and skin and ocular lesions. "Certain genetic syndromes, including Carney complex, neurofibromatosis types 1 and 2 (NF1 and NF2), and tuberous sclerosis complex (TSC), are associated with the development of both cardiac and cerebral tumors." (PMID 40427120, 2025). "Neurofibromatosis type 1 (NF1) and Neurofibromatosis type 2 (NF2), tuberous sclerosis complex (TSC), von Hippel–Lindau disease (VHL), Sturge–Weber syndrome (SWS), and ataxia–telangiectasia (A-T) exemplify this group." (PMID 40558831, 2025). "Genes that are part of this pathway have previously been implicated in various neurological diseases such as Parkinson’s disease (PARK2), frontotemporal dementia (MAPT), neurofibromatosis 2 (NF2), tuberous sclerosis (TSC1)." (PMID 30258056, 2018). "Similarly, we identified a TSC2 variant in all tumours from a patient in whom no NF2 mutations were found and without known tuberous sclerosis (TS)." (PMID 36882706, 2023).
benign meningioma (10 papers, 2015 to 2023). A grade I, slowly growing meningioma. "Similar results were observed in an NF2-deficient benign meningioma cell line, Ben-Men1-LucB, hereafter referred to as Ben-Men, in which expression level diminished by 54% and 58% for Pak1 and Pak2, respectively." (PMID 25596744, 2015). "In this prospective longitudinal study, we assessed volumes and growth rates of ten spinal and ten cranial benign meningiomas in seven NF2 patients that concluded with surgical resection and performed whole-exome sequencing and copy-number variant (CNV) analysis of the tumors." (PMID 32724039, 2020). "All of these studies have found that chr22q/NF2 loss does not co-occur with TRAF7, AKT1, KLF4, SMO, or POLR2A mutations, which were all found in benign meningiomas." (PMID 31652973, 2019). "The primary screen was carried out in triplicate in the NF2-negative benign meningioma cell line Ben-Men-1, using a high-titer lentiviral kinome shRNA library developed by The RNAi Consortium (TRC; Broad Institute/MIT, Cambridge, MA)." (PMID 26219339, 2015).
malignant pleural mesothelioma (10 papers, 2015 to 2024). A malignant neoplasm that arises from mesothelial cells in the pleura and shows a diffuse growth pattern. "NF2-mutations as they relate to Hippo signaling pathway regulation have been studied in human malignant pleural mesothelioma (MPM) cells as well." (PMID 39796693, 2024). "The mutation of NF2 (Neurofibromin 2), a gene to inhibit tumorigenesis, was found in malignant pleural mesothelioma (MPM)." (PMID 34598686, 2021). "Malignant pleural mesothelioma (MPM) is characterized by loss of function or mutations in the neurofibromin 2 (NF2) and the cyclin-dependent kinase inhibitor 2 genes." (PMID 26805820, 2016). "In about 30–40% of malignant pleural mesothelioma cases, for example, the NF2 (Neurofibromatosis type 2) tumor suppressor gene is somatically inactivated, leading to defective recruitment of LATS1/2 kinases to the plasma membrane and impaired Hippo signaling." (PMID 38139762, 2023). "Neurofibromatosis type 2 (NF2), the tumor suppressor frequently lost in malignant pleural mesothelioma (MPM), suppresses tumorigenesis in part by inhibiting the Cullin4 ubiquitin ligase (CUL4) complex in the nucleus." (PMID 33233664, 2020). "To confirm whether TM2 functions through blockade of TEAD-YAP binding, we tested TM2 in malignant pleural mesothelioma (MPM) cell line NCI-H226 cells, which is deficient with NF2 and highly dependent on TEAD-YAP activities." (PMID 36398861, 2022).